CTSL (cathepsin L)
Diseases named in the same sentence as CTSL in open-access papers (continued):
Sharing a sentence is not in itself a finding about the gene and the disease.
infection (continued). "Editing of these genes, including those encoding CTSL, cholesterol transporters NPC1/2, WDR81/91, and TFE3, markedly reduced infection, suggesting that Sdel and SARS-CoV may utilize similar entry machinery in this cell type." (PMID 33574281, 2021). "Further studies showed that inhibitors of cathepsin L blocked infection by both SARS-CoV and pseudotype expressing the SARS-CoV S protein, while not affecting the infection by either HCoV-NL63 or a retrovirus pseudotyped with the HCoV-NL63 S protein in HEK293T cells expressing Cathepsins and ACE2." (PMID 34239932, 2021). "The oxocarbazate, when treated with HEK 293T lysate in the presence of DCG-04, an activity-based cysteine cathepsin probe, showed reduced cathepsin L labeling when assessed by a Western-blot analysis; this further corroborated the results obtained from the virus pseudotype infection assay." (PMID 32041276, 2020). "Cathepsin L-deficient C57BL/6 mice (Ctsl−/−) infected with influenza A (H1N1) virus were not able to limit viral replication during early stages of infection." (PMID 31077130, 2019). "In conclusion, CTSL plays crucial roles in innate and adaptive immune response and may bring about different and even opposite effects on the infections depending on the pathogens." (PMID 30986254, 2019). "During these first few hours of infection, the cathepsin L transcript is upregulated in the host." (PMID 29692003, 2018). "This study was aimed at analysing the dynamic of the cell populations present in peritoneal liquid and the production of free radicals by the peritoneal leukocytes in infected and vaccinated sheep with recombinant cathepsin L1 of F. hepatica (rFhCL1) in early stages of the infection." (PMID 30189903, 2018). "In the freshwater prawn Macrobrachium rosenbergii, the cathepsin L transcript is upregulated in response to bacterial (Vibrio harveyi and Aeromonas hydrophila) and viral (M. rosenbergii nodovirus or white spot syndrome baculovirus) infections." (PMID 29692003, 2018). "However, the findings suggest that CTSL’s dominant contribution is defense against infection, and that its presence in mice limits respiratory viral burden and improves likelihood of surviving infection." (PMID 27716790, 2016). "On these grounds, we hypothesized that CTSL is less likely to be a major in vivo activator of influenza A than to support host defense against infection." (PMID 27716790, 2016). "The present study tested the hypothesis that CTSL protects mice from serious consequences of infection by the orthomyxovirus influenza A, which is thought to be activated by host-supplied proteases other than CTSL." (PMID 27716790, 2016). "Cathepsin L wild type +/+ MEFs (cath L +/+ with HPV16) showed an increase in infection levels (78.38%) compared to cathepsin L -/- deficient MEFs (cath L -/- with HPV16) which had a 60.26% infection level." (PMID 19619315, 2009). "Moreover, we compared the conservation of the two CTSL cleavage sites among seven known human CoVs and found that these CTSL cleavage sites exist only in SARS-CoV-1 and SARS-CoV-2, suggesting that CTSL would play a unique role in the process of SARS-CoV-1/2 infection." (PMID 35668062, 2022). "In addition, the effectiveness of CTSL inhibitors in preventing or treating infections of SARS-CoV-2 virus, remains unknown." (PMID 35668062, 2022). "Moreover, our data also demonstrated that teicoplanin was able to potently inhibit the infection of both live SARS-CoV-2 viruses and different pseudotyped SARS-CoV-2 mutants by inhibiting the enzymatic activity of CTSL and preventing S proteins activation in TMPRSS2-deficient cells." (PMID 35572668, 2022). "In mouse NIH3T3 and rat L6 cells in which the Eco-MLV infection is pH-dependent, levels of the cathepsin L precursor and processed single chain proteins were elevated and reduced by the ConA treatment, respectively, indicating that the ConA treatment suppresses the cathepsin L processing." (PMID 22022555, 2011).
infection (continued). "Alternatively however, and also of interest is that the high infectivity signal and predominance of F0 in the pseudotypes prepared with FΔCt1, FΔCt2 and FΔCt3 could argue for a role of endocytosis followed by Cathepsin L processing of F0 and subsequent productive fusion and infection." (PMID 21073718, 2010). "To confirm the role of CTSL in the inhibitory effect of UNC0638, we overexpressed CTSL in HeLa-ACE2 cells and evaluated pseudovirion infection in the presence of UNC0638." (PMID 40530850, 2025). "CtsL is also essential for DC-mediated adaptive immunity against IAV and mice protection from the severe consequences of infection." (PMID 41369389, 2025). "Cathepsin L (CTSL) and calpain-1 (CAPN1) are host cysteine proteases which play crucial roles in coronaviral entrance into cells and infection-related immune response." (PMID 38443334, 2024). "This condition increased the functionality of CTSL, which cleaved the spike protein of SARS-CoV-2, promoting virus membrane fusion and infection." (PMID 39150053, 2024). "We then conducted a CTSL KO Huh7 cell infection experiment under different glucose conditions, to illustrate the impact of glucose level on SARS-CoV-2 infection via CTSL." (PMID 39150053, 2024). "It has been reported that efficient infection of SARS-CoV and SARS-CoV-2 requires sequential cleavage of S by furin at the S1/S2 site and then by TMPRSS2 at the S2’ site or by CTSL at two specific sites in endosome when TMPRSS2 expression is repressed." (PMID 37196033, 2023). "We used the rescued strain rSczy3 to infect CEKs and performed qRT-PCR to evaluate the relative expression levels of CTSL, CTSB, Abl1, Abl2, IFITM3, ADAM17, TMPRSS2, NRP1, and CD74 at 12 and 24 h post-infection." (PMID 37376546, 2023). "During the productive phase of HSV-2 infection, the upregulation of HPSE correlated with increased levels of cathepsin L, and the inhibition of either HPSE or the cathepsin resulted to be detrimental to the infection." (PMID 36012353, 2022). "The infection by SARS-CoV-2 was mainly mediated by Furin and TMPRSS2, while PCoV-GD and PCoV-GX mainly depend on Cathepsin L. Extensive cross-neutralization was found between SARS-CoV-2 and PCoV-GD." (PMID 33824288, 2021). "Infection with MAH and M. tuberculosis inhibits the maturation of cathepsin L, while infection with M. bovis BCG inhibits expression of cathepsin S." (PMID 31117286, 2019). "For example, by cleaving viral proteins, CTSL helps Ebola, Hendra and Severe Acute Respiratory Syndrome (SARS) viruses infect host cells, thereby advancing these infections." (PMID 27716790, 2016). "In mouse embryonic fibroblasts lacking cathepsin B alone or lacking both cathepsins B and L, VSV-GP∆Muc infection was reduced by >90% and >99%, respectively, indicating an essential role for cathepsin B and an accessory role for cathepsin L in EBOV entry." (PMID 40135892, 2025). "Furthermore, our results illustrate that peptidyl nitroalkenes are effective covalent reversible inhibitors of the Mpro and cathepsin L, and that inhibitors FGA145, FGA146 and FGA147 prevent infection against SARS-CoV-2." (PMID 38238420, 2024). "CTSL and CAPN1 play significant roles in the entry and infection of multiple enveloped viruses and thus may serve as ideal targets for inhibition of diverse coronaviruses." (PMID 38443334, 2024). "Furthermore, OM-ALI cells expressed genes for all the characteristic proteins that are important for viral entry and infection, such as TMPRSS-2, CTSB, CTSL, NRP-1, BSG, and furin." (PMID 38098019, 2023). "hepatica procathepsin L zymogens and showed FhpCL antigens are exposed tothe host immune system in vivo and moreover are secretedas coproantigens, which can be used to indicate treatment efficacyin experimental TCBZ-S/-R infections." (PMID 35849550, 2022). "Here, we further identified that SARS-CoV-2 can utilize human CTSL to assist infection independent of furin." (PMID 35668062, 2022).
infection (continued). "To assess possible cell type–dependent effects, we carried out experiments using Caco-2 target cells and found that cathepsin L inhibitor III and BafA1 robustly inhibited cell-to-cell transmission and cell-free infection of both viruses, in particular SARS-CoV." (PMID 34937699, 2022). "Since andrographolide has the potential to bind with Cathepsin L, it might inhibit the normal Cathepsin L activity for priming of SARS-CoV-2 S protein, and thereby inhibits the endocytosis of the virus particles in cell and infection." (PMID 35812188, 2022). "A limitation of Vero cells as recipients is that mostly CTSL but not TMPRSS2 mediates spike processing unlike in vivo infection of human lung cells with SARS-CoV-2." (PMID 36382127, 2022). "In the absence of TMPRSS2, imatinib was as potent as the cathepsin L inhibitor (E64d) in blocking lenti-Spike infection, suggesting that imatinib inhibits infection in endosomal pathway." (PMID 35388061, 2022). "E64d, a cathepsin L inhibitor, significantly inhibits endosomal SARS-CoV-2 infection mainly in the absence of TMPRSS2 while camostat, a serine-protease-inhibitor, inhibits membrane-fusion-mediated infection in the TMPRSS2 positive cells." (PMID 35388061, 2022). "Endocytosis-related proteins CD44, Rab5, Rab7, and LAMP2 were increased after infection, while the level of Cathepsin L did not change." (PMID 34163451, 2021). "However, at 24 h post-infection, levels of LEP and CTSL were up-regulated (~ 2.1-fold and ~ 1.4-fold respectively)." (PMID 32275661, 2020). "There were greater differences on the levels of CTSL in DCs in most tissues between the infection group and control group, indicating stronger responses of CTSL were present in DCs rather than macrophages." (PMID 30986254, 2019). "For cathepsin L, no significant changes in protein levels were detected after infection with the two species of mycobacteria in M1 macrophages, but there was a slight increase in M0 macrophages after M. smegmatis infection." (PMID 27572605, 2016). "Although ACE2 is a cellular receptor for two divergent coronaviruses, SARS coronavirus and human coronavirus NL63, it was reported that the inhibitors of cathepsin L blocked the infection only by SARS, but not by NL63 virus." (PMID 23305363, 2012). "While virus entry into Vero cells is dependent on the activity of both cathepsin B and cathepsin L, infection of human DCs by EBOV does not require active cathepsin L." (PMID 21927676, 2011). "Additionally, neutrophil elastase can promote rotavirus uncoating and infection in U937 promonocytes, substituting for CTSL to mediate a non-canonical infection pathway." (PMID 41050696, 2025). "While the airway expression of most SARS‐CoV‐2 entry factors may be lower, it is also interesting to focus on those proteins that remained unchanged between COPD and controls, including Furin, CTSL, ADAM17, and ITGA5, as these factors could still facilitate infection." (PMID 41047996, 2025). "We plotted the R-Luc activity (infection efficiency) relative to the measured cell viability (F-Luc) and noted a significant downregulation of infection efficiency relative to cell viability for all three CTSB single guide RNAs and two of three CTSL single guide RNAs." (PMID 38319076, 2024). "However, other cathepsin L inhibitors prevented infection of cells lacking TMPRSS2 when those were incubated with inhibitors prior to SARS-CoV-2 infection." (PMID 38381158, 2024). "Inhibition of cathepsin L also did not significantly block infection." (PMID 37039676, 2023). "We also quantified the relative expression of BSG/CD147, ACE2 (given its involvement in SARS-CoV-2 binding and infection of many cell types), as well as cell surface protease TMPRSS2 and endosomal Cathepsin L (CTSL) in podocytes infected with SARS-CoV-2 for 72 h using different MOIs." (PMID 35517495, 2022).
infection (continued). "In fact, several proteases have been found to be involved in the transmission or infection process, including furin (a membrane-bound protease expressed in different tissues, mainly in the lungs), ADAM17 (short for a disintegrin and metalloprotease 17), and cathepsin L." (PMID 34201505, 2021). "TMPRSS2 plays a dual role in the infection process: it proteolytically cleaves both the S protein, to trigger fusion of viral envelope with the host cell membrane, and the ACE2 tail, to increase the virion uptake, also through the cathepsin L -dependent pathway." (PMID 34201505, 2021). "In addition, cathepsin L (CTSL), a lysosomal protease which is known to mediate the cellular entry of the SARS virus via endosomes by priming the viral spike proteins for membrane fusion, appears to also facilitate the infection of host cells by SARS-CoV-2." (PMID 33066495, 2020). "For many other respiratory pathogens, including the orthomyxovirus influenza A, there are no published data to indicate whether CTSL promotes infection, as suggested for some viral pathogens, or mitigates it, as in mycoplasma infection." (PMID 27716790, 2016). "In addition, expression of exogenous cathepsin L significantly enhanced infection mediated by the SARS S protein, but not by the NL63 S protein or the vesicular stomatitis virus G protein." (PMID 23305363, 2012). "Furthermore, the expression of CTSL in human GCs and CCs suggests the possible activation of membrane fusion within endosomes, thus confirming the ability of SARS-CoV-2 to establish robust infection through endosomal entry, as demonstrated in in vitro cell culture systems." (PMID 35563737, 2022). "However, it still remains obscure whether CTSL contributes to the protections from the infection by mucosal immune responses or not since there are little direct or indirect evidences available for now." (PMID 30986254, 2019). "Further strengthening this suggestion, cathepsin inhibitor 1, which inhibits endosomal cathepsin L crucial for SARS-CoV-2 endosomal fusion and infection, nearly abolished V-EGFP expression without affecting V-A647 uptake." (PMID 40964294, 2025). "The cathepsin L specific inhibitor, CLIK148, did not affect the mNDK vector infection in CD4-negative and –positive cells (data not shown)." (PMID 21541353, 2011). "Furthermore, they blocked the activity of cathepsins B and B/L by CA074 and FYdmk, respectively, using a range of concentrations, and found that the extent of inactivation of cathepsin B, but not cathepsin L, closely correlated with VSV-GP∆Muc infection percentage." (PMID 40135892, 2025). "While no changes in renal cathepsin L levels were observed in DHT-treated mice in LFD, it was significantly upregulated by DHT in HFD-fed mice, suggesting a pathway for increased renal SARS-CoV-2 viral entry by endocytosis following infection in obese women with PCOS." (PMID 34575910, 2021).
bacterial infection (5 papers, 2021 to 2024). "Dengue non-structural protein 1 (NS1) directly induces glycocalix shedding of lung endothelium through the upregulation of cathepsin L, endothelial sialidases, and heparanase through TLR-4, similar to bacterial infection via LPS." (PMID 36671689, 2023). "Presumably, CTSL is significantly upregulated to ensure mussels do not suffer from bacterial infection under prolonged starvation and participate in the apoptotic pathway." (PMID 37064882, 2023). "We previously reported that teicoplanin, a glycopeptide antibiotic that has been commonly used in the clinic to treat bacterial infection, significantly restrained the cell entry of Ebola virus, SARS-CoV, and MERS-CoV by specifically inhibiting the activity of cathepsin L (CTSL)." (PMID 35572668, 2022).
cardiovascular diseases (5 papers, 2016 to 2025). "Cysteine cathepsins, including cathepsin L, have been implicated in the development and progression of cardiovascular diseases." (PMID 41439980, 2025). "The role of CD74 in cardiovascular disease is significant, with CD74 regulating extracellular cathepsin L activity." (PMID 41439980, 2025).
neurodegenerative disease (4 papers, 2016 to 2025). A disorder of the central nervous system characterized by gradual and progressive loss of neural tissue and neurologic function. "Our findings implicate that enhancing the activity or levels of CtsB and/or CtsL could provide a promising and a common strategy for maintaining lysosomal function, clearance of the aggregation prone proteins and for preventing and/or treating neurodegenerative diseases." (PMID 27902765, 2016).
colon (2 papers, 2021 to 2022). "We therefore characterized the expression profiles of a number of genes involved in SARS-CoV-2 infection pathway and found higher ACE2, TMPRSS2, TMPRSS4, SCARB1, CTSL and NRP1 expression in all GI tumor samples relative to their normal counterparts." (PMID 35970857, 2022).
head and neck tumour (2 papers, 2025). "Through GSEA analysis, we revealed the mechanism by which CTSL acts through the IL6‐JAK‐STAT3 pathway in head and neck tumours." (PMID 39893643, 2025). "These in vivo results further suggest that USP20 plays a key role in promoting head and neck tumour progression by stabilizing CTSL." (PMID 41261048, 2025).
brain disease (1 paper, 2022). "Taken together, our findings add to an increasing body of evidence indicating that cathepsin L and its nuclear targets play central roles in brain disease." (PMID 36533126, 2022).
vasculopathy (1 paper, 2023). "Enhanced expression of endothelial cathepsin B and cathepsin L due to Fli1 deficiency has been shown to be associated with SSc vasculopathy, whereas downregulation of CTSB, CTSL, and CTSV in dermal fibroblasts implicates in SSc dermal fibrosis." (PMID 36768203, 2023).
CTSL also shares sentences with these, for which no sentence is quoted: renal disease (7 papers); dilated cardiomyopathy (4); schistosomiasis (4); asthma (3); Chagas disease (3); hepatocellular carcinoma (3); infectious disease (3); adenocarcinoma (2); autoimmune disorder (2); colon adenocarcinoma (2); Ebola (2); gall bladder (2); infertile (2); liver cancer (2); lysosomal storage disorders (2); Pancreatic Neuroendocrine Cancer (2); psoriasis (2); rectal adenocarcinoma (2); Stomach adenocarcinoma (2); acute respiratory distress syndrome (1); adenomyosis (1); adrenocortical carcinoma (1); adrenocortical tumors (1); alopecia (1); autoimmune type 1 diabetes (1); cardiomyopathy (1); chondrosarcoma (1); Chronic colitis (1); chronic lung disease (1); chronic obstructive pulmonary disease (1).
A further 66 diseases each share a sentence with CTSL in 1 paper.